ABCG2 (ATP binding cassette subfamily G member 2 (JR blood group))
Diseases named in the same sentence as ABCG2 in open-access papers (continued):
Sharing a sentence is not in itself a finding about the gene and the disease.
hyperuricemia (continued). "In conclusion, our study showed that Yi‐Suan‐Cha significantly reduced serum uric acid level in hyperuricemia rats, possibly by downregulating the expression of URAT1 and GLUT9 and upregulating the expression of ABCG2 and OAT1." (PMID 34251052, 2021). "We summarized the change trend with the time of plasma uric acid level, uric acid clearance rate, and the expression levels of ABCG2, URAT1, GLUT9, OAT1 and NPT1 in hyperuricemia mice." (PMID 32707836, 2020). "Notably, ABCG2 mRNA expression levels of the high and middle doses of chicory were increased to 231.34% and 383.17% in jejunum, and protein expression levels of them in jejunum were markedly enhanced to 153.98% and 199.33% by western blotting, when compared with hyperuricemia rats respectively." (PMID 28630638, 2017). "Additionally, the changed gut microbiota affects the expression of UA transporters in the intestine, including ABCG2 and GLUT9, as well as the ongoing inflammatory response, both of which aid in the development of hyperuricemia." (PMID 38674582, 2024). "Furthermore, a study examined that L. rhamnosus Fmb14 cell-free-extract treatment ameliorates hyperuricemia through the inhibition of XOD and increases the expression of ABCG2 UA transporter." (PMID 38674582, 2024). "Fisetin (3,3′,4′,7-tetrahydroxyflavone), a naturally occurring flavonol, reduces serum urate by modulating the expression of kidney urate transporters, including Urat1, Oat1/3, and Abcg2, via the STAT3 and TGF-β signaling pathways in mice with PO- and adenine-induced hyperuricemia." (PMID 36483739, 2022). "When treating patients with hyperuricemia who want to avoid accumulation of IS in the body, a hypouricemic agents that do not inhibit OATs or ABCG2, such as dotinurad, are desirable." (PMID 33790363, 2021). "From the GO analysis, we could draw that ABCG2, URAT1, and GLUT9 transporter proteins play critical roles in hyperuricemia and kidney excretion." (PMID 35083262, 2021). "In addition, the expression levels of GLUT9 and URAT1 were upregulated from the 3rd day, while ABCG2 and OAT1 were downregulated from the 3rd day, and NPT1 were downregulated from the 7th day in hyperuricemia mice kidney." (PMID 32707836, 2020). "In addition, the expression levels of urate transporters GLUT9 and URAT1 were upregulated from the 3rd day, while urate transporters ABCG2 and OAT1 were downregulated from the 3rd day, and NPT1 were down regulated from the 7th day in hyperuricemia mice kidney." (PMID 32707836, 2020). "However, the expression of urate transporters ABCG2, OAT1 and NPT1, which promote the secretion of uric acid, decreased significantly from the 3rd day to the 21st day in hyperuricemia mice." (PMID 32707836, 2020). "The protein expression of ABCG2 and OAT1 in the kidney was increased, and the protein expression of GLUT9 and URAT1 was downregulated; these effects reduce serum uric acid concentration, thereby preventing the occurrence of hyperuricemia." (PMID 31185695, 2019). "In addition, compared with the normal group, the ABCG2, OAT1, and NPT1 protein expressions were significantly decreased in the hyperuricemia control group (p < 0.01)." (PMID 31920654, 2019). "Recently, we and other research groups have independently found that ABCG2 is a physiologically important regulator of urate as well as URAT1, a major component of the urate reabsorption system in the kidney and a target of hyperuricemia therapy." (PMID 28082903, 2016). "Since allopurinol, febuxostat, topiroxostat and benzbromarone are the major SUA-lowering drugs presently known, the development of SUA-lowering drugs that do not inhibit ABCG2 would be the next strategy for developing a more effective hyperuricemia therapy." (PMID 28082903, 2016). "Increased expression of intestinal ABCG2 may be effective for eliminating UA from the body and alleviating the symptoms of hyperuricemia, suggesting that LP06CC2 may provide a new strategy for the treatment or prevention of hyperuricemia." (PMID 39275356, 2024).
hyperuricemia (continued). "Therefore, we suggest that hypouricemic agents that do not affect OATs and ABCG2 are effective therapeutic options for the treatment of hyperuricemia complicated by CKD." (PMID 33790363, 2021). "In addition, the expression of the ABCG2 and OAT1 transporter proteins in the hyperuricemia group was significantly lower than that of the control group, whereas treatment of hyperuricemia mice with nuciferin significantly increased the expression of ABCG2 and OAT1 proteins." (PMID 31185695, 2019). "However, neither hyperuricemia nor estradiol changed the renal expression of ABCG2." (PMID 34144706, 2021). "In contrast, ABCG2 rs12505410 genotype groups were not correlated with both SUA levels and hyperuricemia (p > 0.05)." (PMID 30621105, 2019).
lung carcinoma (171 papers, 2006 to 2026). "CD133 (Prominin 1) has been used to identify CSCs in lung cancer and was linked to high levels of ABCG2 and chemoresistance." (PMID 31446534, 2020). "Since aberrant EGFR signaling is implicated with the initiation and progression of lung cancer, we first assessed SP frequency and expression of ABCG2 in the presence of an antagonistic antibody against EGFR." (PMID 23009336, 2012). "Previous studies have detected SP phenotype with higher ABCG2 expression level and implicated ABCG2 as a CSC marker in lung cancer A549 cells." (PMID 22768056, 2012). "Furthermore, the associations of ABCG2 expression with clinicopathological and demographic features in lung cancer were evaluated." (PMID 39457707, 2024). "Based on the postulated mechanisms, GLI1 inhibition may lead to the downregulation of its target genes, including stemness-related SOX2 and ABCG2 in lung cancer cells, thus underlying its potential therapeutic interference." (PMID 37149646, 2023). "Moreover, we examined the expression of LSH, LSH-p503, and stem cell-associated marker ABCG2 in lung tissue derived from lung cancer patients through immunohistochemistry (IHC) analysis." (PMID 32994405, 2020). "Similarly, TMP195 resensitized S1-M1-80 cells and H460-MX20, an ABCG2-overexpressing MDR variant of H460 human lung cancer cells, to SN-38 and topotecan in a concentration-dependent manner." (PMID 31905792, 2019). "Telmisartan (7a)significantly inhibited the SP phenotype of ABCG2+ MCF-7 breast cancerand ABCC1+ A549 lung cancer cells, but only modestly affected ABCB1+A2780 V SP and IGROV-1 SP ovarian and PC3-DR and DU145-DR prostatecancer cells." (PMID 39693499, 2025). "The expression of ABC sub-family G member 2 (ABCG2) in the lung cancer cell line NCI-H460/MX20 after treatment with QB1561 was assessed by Western blot." (PMID 40066335, 2025). "In this study, we evaluated the selective toxicity of tinodasertib in ABCG2-overexpressing lung cancer MCTSs to better understand its potential as a reversal agent in a three-dimensional tumor microenvironment." (PMID 40584625, 2025). "Initially, gefitinib-resistant lung cancer cells exhibited stemness characteristics, including an epithelial-to-mesenchymal transition phenotype and elevated ABCG2 expression, which were closely regulated by c-kit." (PMID 39744423, 2025). "In non‐small cell lung cancer, ABCG2 expression was found to be significantly lower in primary cancer tissues compared to healthy tissue." (PMID 40874518, 2025). "In summary, USP24-i targeting USP24 activates autophagy to promote the degradation of ABCG2 and PD-L1, leading to the inhibition of drug resistance acquired from lung cancer therapy." (PMID 38491202, 2024). "Our observations revealed more sensitivity to MTX-211 in parental human S1 colon cancer cells and H460 lung cancer cells compared to their respective ABCG2-overexpressing counterparts, S1-MI-80 and H460-MX20." (PMID 38791198, 2024). "In line with that, ABCG2 was shown to be upregulated in some lung cancer cells, including A549, in response to smoke exposure." (PMID 38442133, 2024). "Specifically, we focused on the role of ATP-binding cassette G2 (ABCG2), which has been previously shown to be highly expressed in some lung cancer cell lines, including an adenocarcinoma cell line A549." (PMID 38442133, 2024). "The dual TTK/CLK2 inhibitor CC-671 provides a theoretical basis for overcoming ABCG2-mediated MDR in lung cancer patients." (PMID 38195567, 2024). "On the other hand, ABCG2 expression is high in SP cells isolated from lung cancer cell lines and other tumor cell lines." (PMID 39457707, 2024). "It is the first such investigation, and thus the unequivocal exclusion of correlation between the ABCG2 expression in blood and general effectiveness of anticancer treatment in patients with lung cancer is impossible." (PMID 39457707, 2024).
lung carcinoma (continued). "SP cells isolated from lung cancer cell lines demonstrated a higher level of ABCG2 at the mRNA and protein levels, providing them a broad spectrum of drug/xenobiotics resistance." (PMID 39457707, 2024). "In summary, ABCG2 is strongly involved in immunoinfiltration in lung cancer and therefore remains a promising target for immunotherapy related to immune cell infiltration." (PMID 39457707, 2024). "In this study, we evaluated the potential of the ALA-hemin combination in enhancing the therapeutic effects of ALA-PDT against human lung cancer by regulating ABCG2 and ABCB1 expressions with hemin." (PMID 39584916, 2024). "Next, we divided the lung cancer patients according to the histological subtype and investigated the correlation of ABCG2 expression with the prognosis of patients within LUAD, LUSC, and both subtypes combined." (PMID 39457707, 2024). "In vitro, MK-2206 significantly increased the efficacy of the anticancer drugs, mitoxantrone, SN-38 and topotecan, in MDR H460/MX20 lung cancer cells overexpressing the ABCG2 transporter." (PMID 37521473, 2023). "On the other side, exogenous expression of SOX4 significantly abrogated the CCAT1-knockdown-mediated cisplatin sensitivity and ABCG2 lower expression in cisplatin-resistant lung cancer cells." (PMID 36778005, 2023). "Encouragingly, however, a protein kinase AKT1/2/3 inhibitor, MK-2206, has been shown to reverse the ABCG2-mediated MDR response of lung cancer cells to mitoxantrone, SN-38 and topotecan." (PMID 38169723, 2023). "By pumping chemotherapeutic medications out of cells and lowering the concentration of intracellular pharmaceuticals, ABCG2 significantly increased the chemotherapy resistance of lung cancer stem cells." (PMID 37144123, 2023). "Multidrug resistance (MDR) caused by lung cancer stem cells correlates with the expression of ABCB1 and ABCG2." (PMID 37144123, 2023). "A previous study has shown that intraperitoneal administration of MTE can suppress the activity of ABCG2 in lung cancer xenografts." (PMID 36756719, 2023). "In this study, our results indicated that MK-2206, at 0.3 and 1 μM, did not significantly decrease the viability of the parental H460 and ABCG2-overexpressing H460/MX20 lung cancer cells and parental S1 and MDR ABCG2-overexpressing S1-M1-80 colon cancer cells." (PMID 37521473, 2023). "A possible novel role of ABCG2 within the nucleus as a transcriptional regulator involved in modulation of metastasis has been proposed in lung cancer." (PMID 36982894, 2023). "Consistent with enriched CD133+ cells from human lung cancer cell lines, coexpression of elevated ABCG2 was observed in these spheres." (PMID 35956408, 2022). "A mechanistic study showed that the constitutive expression of redox-sensing NRF2, in addition to ABCG2, is involved in eliciting chemoresistance to chemotherapeutics in lung cancer SP cells." (PMID 35053430, 2022). "An altered methylation pattern was detected in the promoters of ABCB1, ABCC1, and ABCG2 in breast and lung cancer, whereas the defective activity of histone acetylases including EP300, CBP, and PCAF was reported to be implicated in ABCB1 overexpression." (PMID 35205642, 2022). "The authors proposed that the SAD mechanism of action consists of the ability to down-regulate the expression of ABCG2 and decrease the percentage of SP cells in lung cancer cells due to the induction of ABCG2 degradation by calpain 1 activation." (PMID 35736150, 2022). "On this basis, the constitutive expression of redox-sensing NRF2, in addition to ABCG2, was found to be involved in eliciting tolerance to chemotherapeutics in lung cancer SP cells." (PMID 35053430, 2022). "The relationship among USP24, ABCG2, and cancer stemness markers was then studied in clinical lung cancer cohorts." (PMID 33846536, 2021).
lung carcinoma (continued). "Nuclear localization of ABCG2 has previously been reported in glioblastoma multiforme cells and also in lung cancer cells, where decreased ABCG2 expression was connected with down-regulation of E-cadherin and enhanced motility of cancer cells." (PMID 33917029, 2021). "Meanwhile, we found a similar decrease of drug-resistant genes (ABCB1, ABCC1, and ABCG2) in lung cancer spheroids after apatinib treatment, which was further confirmed in CDDP-resistant A549 cells." (PMID 33980809, 2021). "In the study of lung cancer, it was found that when ENPP1 gene was knocked out in lung cancer cell lines, the expression of a large number of stem cell markers decreased, including ABCG2, SOX2, NANOG, and CD44." (PMID 33635867, 2021). "ABCG2 transporters are not only responsible for secreting riboflavin into the milk in lactating mammary glands, but also for transporting and mediating a marked intravesicular accumulation of riboflavin in ABCG2–overexpressing breast and lung cancer cells." (PMID 33669350, 2021). "Tobacco is well known to promote tumor resilience through the Akt-mediated ABCG2 activity to increase the proportion of lung cancer and HNSC tumor stem-like cells." (PMID 34796198, 2021). "The data indicated a highly positive correlation between the levels of USP24 and ABCG2 in patients with lung cancer." (PMID 33846536, 2021). "The presence of CD133-positive CSCs in lung cancer increases the expression of the ABC transporter ABCG2, resulting in lung cancer resistance to first-line drugs such as platinum and paclitaxel." (PMID 33588867, 2021). "Cancer resistance protein ATP-binding cassette subfamily G member 2 (ABCG2) is presented primarily in stem cell membranes of lung cancer tumors." (PMID 35582384, 2021). "In lung cancer patients, clinical studies have shown a correlation between therapeutic outcome and ABCG2 expression level." (PMID 32477940, 2020). "Findings for MDR cell line models suggest that changes in ABCB1 and ABCG2 promoter methylation are involved in acquiring MDR in lung cancer." (PMID 33066132, 2020). "The ABCG2 is a suggested molecular determinant of the side population (SP) phenotype, and the expression of ABCG2 mRNA was markedly higher in SP for all lung cancer cell lines analyzed." (PMID 32397297, 2020). "ABCG2 expression has been found to be inversely correlated with ABCG2 promoter methylation status in both lung cancer subtypes." (PMID 33066132, 2020). "NRF2 knockdown in lung cancer cells depleted their ABCG2 levels and sensitized them to the chemotherapeutic drugs mitoxantrone and topotecan." (PMID 32629871, 2020). "In summary, three studies have investigated ABCB1 and three studies ABCG2 promoter methylation in lung cancer." (PMID 33066132, 2020). "ABCG2 is a key transporter related to resistance to anticancer agents and is expressed by various cancers, including lung cancer and colorectal cancer." (PMID 31340525, 2019). "The inhibitor of ABCG2 induced the drug efficacy of mitoxantrone and topotecan to lung cancer cells which overexpress ABC transporters." (PMID 35582573, 2019). "Cigarette smoke condensate enhanced drug resistance of lung cancer cells, a phenomenon mainly related to enhanced expression of the drug exporter ABCG2." (PMID 30060526, 2018). "MiR-221 together with proteins MDR1 and ABCG2 was upregulated in Cisplatin-resistant A549 lung cancer cells." (PMID 29876362, 2018).